PRAME (PRAME nuclear receptor transcriptional regulator)
Diseases named in the same sentence as PRAME in open-access papers (continued):
Sharing a sentence is not in itself a finding about the gene and the disease.
melanoma (continued). "In recent years, PRAME (preferentially expressed antigen in melanoma) has gained popularity." (PMID 40843873, 2025). "In summary, while diffuse PRAME expression is found in some cases of nested melanoma, it does not provide sufficient diagnostic assistance, particularly in cases without pagetoid intraepidermal spread of melanocytes." (PMID 40941765, 2025). "The aim was to determine whether PRAME is a reliable immunohistochemical marker for distinguishing between nested melanoma and benign nevi." (PMID 40941765, 2025). "PRAME, a melanoma-associated antigen, is a highly sensitive and specific marker for melanoma and is typically negative in benign nevi." (PMID 40984891, 2025). "Similarly, PRAME expression of ≥50% melanomas (80%), 9 of 10 LM (90%), and in all cases of NM, ALM, LMM and mucosal melanomas (100%)." (PMID 41153267, 2025). "Also, in a melanoma cell line, it has been shown that the down-regulation of microRNA-211 results in PRAME up-regulation by affecting 2 binding sites in the PRAME 3′ untranslated region (3′-UTR)." (PMID 40961095, 2025). "Interestingly, diffuse PRAME positivity is more frequently reported in melanomas in chronically sun-damaged skin and in older patients compared to cases with low cumulative UV damage." (PMID 40941765, 2025). "Notably, while previous documentation exists of PRAME expression in a few dedifferentiated melanomas with rhabdomyoblastic differentiation, this study marks the first report of its expression in cases with chondrosarcomatous differentiation." (PMID 39625060, 2025). "Most notably, the tumor was positive for PRAME, a tumor-associated nuclear antigen overexpressed in melanoma but typically absent in benign nevi." (PMID 40520839, 2025). "Within a single tumor mass, such as in melanoma, only subsets of cancer cells may display the PRAME antigen on HLA class I molecules, leaving others undetectable to CD8+ T cells." (PMID 40868240, 2025). "Indeed, recent studies indicate that high PRAME expression correlates strongly with malignant melanoma and can be useful in distinguishing melanoma from other clear cell tumors, including CCS." (PMID 40004764, 2025). "Moreover, melanoma cells with SOX9 overexpression restore sensitivity to RA treatment as a result of decreasing PRAME expression." (PMID 40961095, 2025). "This study evaluates the diagnostic performance of PRAME, a tumor-associated antigen, to molecular testing in 34 diagnostically challenging and 9 non-diagnostically challenging melanomas." (PMID 40227827, 2025). "Moreover, elevated PRAME expression was found to be related with earlier metastasis and melanoma-specific mortality in patients with DecisionDX-UM class 2 tumors." (PMID 40380030, 2025). "An emergency craniectomy was performed, and the pathological examination revealed malignant melanoma transformation characterized by a high proliferative index (Ki-67: 50%) and diffuse nuclear PRAME positivity with concordant strong SOX10 and HMB-45 expression (and only weak/focal S100)." (PMID 41294657, 2025). "Preferentially expressed antigen in melanoma (PRAME), a marker that was developed primarily for the diagnosis of melanoma, is a nuclear receptor, transcriptional regulator, and a member of the cancer testis antigen family of proteins that regulates cell differentiation, growth, and apoptosis." (PMID 40599504, 2025). "PRAME is a target for BiTE therapy because it is frequently overexpressed in various cancers, including melanoma, but its expression is limited in normal tissues, which may reduce potential off-target effects and increase the therapeutic index of treatments." (PMID 39857682, 2025). "Finally, preferentially expressed antigen in melanoma (PRAME) serves as an independent biomarker capable of identifying higher-risk subgroups among patients with Class 1 or disomy 3 tumors." (PMID 40380030, 2025).
melanoma (continued). "Hence, when dealing with a metastatic disease, relying solely on PRAME expression for diagnosing melanoma is insufficient, and confirmation through supplementary immunohistochemical or molecular analyses is essential." (PMID 38338862, 2024). "Therefore, the expression profile of PRAME in melanoma and the specificity of this new immunotherapy suggest its potential utility." (PMID 39337333, 2024). "As our understanding of the molecular landscape of melanoma advances, PRAME could serve as a valuable biomarker for early detection." (PMID 38338862, 2024). "Melanoma and Merkel cell carcinoma both fall within the histopathological differential diagnosis of blue cell tumours, so it would be prudent to note that some Merkel cell carcinomas show a diffuse high-intensity expression of PRAME." (PMID 38338862, 2024). "Thus, PRAME expression in melanoma can be negatively controlled by TET2-mediated 5hmC epigenetic modification." (PMID 39091741, 2024). "In addition to being expressed in melanoma patients, PRAME has also been found to be overexpressed in AML patients but not in normal hematopoietic tissues." (PMID 38596687, 2024). "Taken together, our data uggest that 5hmC loss, likely due to the down-regulation of TET2, plays an important role driving PRAME activation and that this may help drive melanoma malignant transformation and progression." (PMID 39091741, 2024). "Also, BCCs, SCCs, and sebaceous carcinomas exhibited low levels of PRAME immunoreactivity, with variable proportions of cases showing nuclear staining, similar to melanoma." (PMID 39727621, 2024). "Additionally, four clusters of gene families, including preferentially expressed antigen of melanoma (PRAME), olfactory receptor (OR), G antigen (GAGE), and melanoma-associated antigen (MAGEA), exhibited dense clusters of SDs with paralogous genes." (PMID 38671502, 2024). "Median PRAME expression was highest in melanomas and lowest in synovial sarcomas." (PMID 38541782, 2024). "In addition, preferentially expressed antigen in melanoma (PRAME) is used clinically to differentiate benign melanocytic nevi from melanoma." (PMID 38927967, 2024). "The inverse relationship between these markers in both melanoma precursor fields and during melanoma evolution suggests that 5hmC may regulate PRAME gene expression directly." (PMID 39091741, 2024). "It is well established that desmoplastic melanomas typically exhibit lower PRAME expression." (PMID 39451258, 2024). "However, it is worth noting that PRAME is very highly expressed in melanoma, with over 95% expression in cutaneous melanoma and over 90% in uveal melanoma." (PMID 39337333, 2024). "C32 melanoma cells show intermediate levels of PRAME-pHLA complexes." (PMID 39659431, 2024). "Similarly, PRAME previously elicited a robust immune response in leukemia and melanoma, and CCNA1 was adopted as a vaccine target for acute myeloid leukemia." (PMID 39136024, 2024). "Indeed, an anti-PRAME monoclonal antibody (EPR 20330) is already being used for the detection of malignant melanoma." (PMID 39659431, 2024). "Advancements in TCR-engineered therapies and modifications to CAR T-cell technology may provide a pathway to effectively target PRAME in solid tumors like melanoma." (PMID 39451258, 2024). "The higher mutational burden and distinct immune responses observed in V600K melanomas suggest that PRAME expression could potentially differ from other subtypes." (PMID 39451258, 2024). "Furthermore, the agreement between morphological data and PRAME expression was evaluated for the diagnosis of melanoma components and nevus components." (PMID 38254769, 2024). "Moreover, PRAME expression has also been reported in various types of malignant tumor, other than malignant melanoma, including myxoid liposarcoma, synovial sarcoma, neuroblastoma, renal cell carcinoma, non-small-cell lung cancer, and thymic cancer." (PMID 38132219, 2023).
melanoma (continued). "Preferentially expressed antigen of melanoma (PRAME) is a small human protein which is seldom expressed in the cytosol of normal cells (it is found in small amounts in the cytosol of cells of the male reproductive system) but is present in the membrane of melanoma and acute leukemia tumor cells." (PMID 36982208, 2023). "PRAME (PReferentially expressed Antigen in MElanoma), a cancer-testis antigen expressed in normal and neoplastic tissues with several functions, proved to be a useful diagnostic tool in the differential diagnosis between benign and malignant melanocytic lesions." (PMID 36912431, 2023). "In cases of pigmented EPC with atypical clinical and dermoscopical characteristics, immunohistochemical markers such as HMB-45, Melan-A and PRAME (Ab219650) may be used towards a differentiation from melanocytic lesions, including melanoma." (PMID 37189532, 2023). "For ambiguous cases, other markers such as WT1 or PRAME help confirm melanoma diagnoses." (PMID 37373134, 2023). "PRAME, a cancer testis antigen first isolated in tumor-reactive T cell clones from metastatic melanoma, is highly abundant and acts as a prognostic marker for several cancers including melanoma and ovarian adenocarcinoma." (PMID 37728703, 2023). "According to the data and as we could observe in our validation cohort, a high PRAME expression is strongly suggestive of melanoma, although melanoma cannot be fully excluded when PRAME expression is low." (PMID 37047361, 2023). "\PRAME, first described as a melanoma antigen, is known to repress retinoic acid receptor signaling and to repress the transcription of genes involved in growth arrest, differentiation, and apoptosis in melanoma models." (PMID 37152992, 2023). "Preferentially expressed antigen in melanoma (PRAME) is one of the cancer/testis antigens." (PMID 38132219, 2023). "Also, in another study, Ricci and his colleagues found that head and neck mucosal melanomas are characterized by PRAME expression." (PMID 37898793, 2023). "PRAME (PReferentially expressed Antigen in Melanoma) is a gene first identified in melanoma." (PMID 37877026, 2023). "All melanoma cases showed PRAME nuclear expression, which was usually widespread and strong." (PMID 35328098, 2022). "Upregulation of preferentially expressed antigen in melanoma (PRAME) has been reported to be a common event in melanomas, and relatively recently, immunohistochemistry for PRAME has been shown to be diagnostically helpful in evaluating various melanocytic lesions." (PMID 35530873, 2022). "One of the CTAs, the PRAME protein, was originally discovered in a human melanoma cell line." (PMID 35386283, 2022). "PRAME expression in melanoma cells is regulated by many actors." (PMID 35328098, 2022). "The downregulation of TRAIL in BCR-ABL1-positive cells is mediated by a preferentially expressed antigen of melanoma (PRAME)/enhancer of zeste homolog 2 (EZH2) repression mechanism, and the inhibition of either PRAME or EZH2 expression increases TRAIL levels and sensitivity to TRAIL and to imatinib." (PMID 35057108, 2022). "The effect of methylation on MZF1-targeted DNA binding motifs has previously been described for the reprogramming key gene OCT4 in induced pluripotent stem cells, the PAX2 gene in endometrial cancer, and the tumour antigen PRAME (preferentially expressed antigen in melanoma) in melanoma cells." (PMID 35409379, 2022). "PRAME (preferentially expressed antigen in melanoma), a member of the cancer-testis antigen family, has been reported to be frequently overexpressed in many cancers, including melanoma, which indicates advanced cancer stages and poor clinical prognosis." (PMID 36613491, 2022).
melanoma (continued). "PMEL, S100B, SERPINE2, TYR, and PRAME were highly expressed in tumor cells and could be the marker genes for melanoma." (PMID 35646893, 2022). "Moreover, PRAME (preferentially expressed antigen in melanoma) recently emerged as a novel marker for the diagnosis of melanoma." (PMID 35328198, 2022). "PRAME promotes the colony formation of melanoma cells in vitro and tumor growth in vivo." (PMID 34359765, 2021). "Immunohistochemical expression of PRAME might be useful in the differential diagnosis of malignant melanoma." (PMID 34195089, 2021). "Thus, the association of PRAME, CXCL9, CXCL10, S100A7, S100A8, and S100A9 with melanoma progression is supported by prior studies and commercially available clinical tests." (PMID 35008167, 2021). "However, subsequent studies from other groups found lower PRAME expression in both primary and metastatic melanomas, calling into question a generally applicable cut-off for melanomas." (PMID 34359765, 2021). "Melanomas and severely dysplastic nevi with PRAME immunoreactivity had different staining patterns." (PMID 34359765, 2021). "Both CD4+ and CD8+ T-cells specific for PRAME, a melanoma antigen, could be expanded from the peripheral blood of healthy donors." (PMID 34526999, 2021). "PRAME was first discovered in 1997 as a tumor antigen in human melanoma cells." (PMID 34074333, 2021). "In melanoma, the preferentially expressed antigen of melanoma (PRAME) is another example of a CTA; PRAME is defined as a testis-selective rather than a testis-restricted CTA as its expression has been observed in endometrial, ovarian, and adrenal gland tissues in addition to testis tissue." (PMID 32585818, 2020). "Interestingly, the 1p36.21 region contains a gene family named PRAME (preferentially expressed antigen of melanoma), which is expressed in many cancers and was functions in reproductive tissues during development." (PMID 31570735, 2019). "These T cells were able to recognize various PRAME-expressing cell lines derived from melanoma, acute myeloid leukemia, colon carcinoma, cervix carcinoma, and lung and breast cancer, whereas acute lymphoblastic leukemia cells were only recognized after CD40L-activation of the T cell clones." (PMID 31311081, 2019). "In accordance, differences in PRAME expression were found among 14 single cell clones derived from a single cutaneous melanoma lesion, suggesting that the presence of low expressing cell clones may allow cancer cells to escape PRAME-targeted immunotherapy." (PMID 31311081, 2019). "The most upregulated gene was PRAME (preferentially expressed antigen of melanoma)." (PMID 31391080, 2019). "PRAME is re-expressed in a wide range of cancers, including melanoma, renal cell cancer, non-small cell lung cancer (NSCLC), neuroblastoma, breast cancer, multiple myeloma, acute leukemia, chronic myeloid leukemia, multiple sarcoma subtypes, and primary and metastatic uveal melanoma." (PMID 31311081, 2019). "PRAME (preferentially expressed antigen in melanoma) is a cancer-testis antigen, firstly discovered in a patient with melanoma, that is expressed by several solid tumors (i.e., squamous cell lung carcinoma, medulloblastoma, renal cell carcinoma, and acute leukemia), including NB." (PMID 30510968, 2018). "While PRAME (preferentially expressed antigen on melanomas) shows only minute expression in healthy tissues, high expression was found in diverse cancers like acute or chronic lymphoblastic or myeloid leukemia, making it an interesting target for T cell-based therapy." (PMID 29707134, 2018). "PRAME (preferentially expressed antigen in melanoma), a member of the cancer-testis antigen family, has been shown to have increased expression in solid tumors, including sarcoma, and PRAME-specific therapies are currently in development for other cancers such as melanoma." (PMID 28630682, 2017).
melanoma (continued). "One of these utilizes the antigen PRAME (preferentially expressed in melanoma) involved in retinoic acid receptor repression although expressed in low levels in many normal tissues and is overexpressed in both melanoma and NSCLC and therefore a vaccination target." (PMID 25374843, 2014). "The PRAME gene was discovered by Ikeda and his colleagues in a melanoma patient in 1997." (PMID 23691459, 2012). "However, most of the melanoma associated antigens, including the MAGE genes, PRAME, S100A8, TRAG3 and MMP19, were more highly expressed in the MM samples than in NHEM." (PMID 18442402, 2008). "PRAME was first identified as an antigen in human melanoma by virtue of patient CTLs." (PMID 19662193, 2007). "Several genes not previously known to be upregulated by hypoxia included Ribonuclease 4 RNAse4 3.1-fold, monocarboxylate transporter family member 4 (SLC16A3 also called MCT4), Preferentially expressed antigen of melanoma PRAME 4.9-fold and Importin Beta 3 4.1-fold." (PMID 16052224, 2005). "Similarly, hypomethylation, in cooperation with MZF1, enhances PRAME expression in melanoma." (PMID 40961095, 2025). "Importantly, PRAME may also carry prognostic value and offers promise as a therapeutic target in melanoma immunotherapy." (PMID 40868240, 2025). "This suggests that more aggressive melanomas may exhibit higher levels of PRAME expression." (PMID 41155720, 2025). "Thus, we found lower PRAME positivity in nested melanoma than in other melanoma subtypes." (PMID 40941765, 2025). "Also, acral and subungual melanomas exhibit PRAME positivity." (PMID 40507250, 2025). "However, the gold standard is only the labeled diagnosis of “desmoplastic melanoma”, and PRAME expression in the PRAME+ desmoplastic melanomas may be signaling something fundamentally different about these desmoplastic melanoma types." (PMID 39451258, 2024). "Furthermore, of the 15 melanoma metastases in the lymph nodes, 100% were PRAME-positive." (PMID 39451258, 2024). "However, PRAME expression may be less sensitive or specific depending on melanoma subtypes, and interpreting weak immunoreactivity can be challenging." (PMID 39408752, 2024). "In this case, the use of PRAME as an immunohistochemical marker could be a valuable diagnostic aid; indeed, PRAME, which is expressed in melanoma but not in most sarcomas, could be an important discriminatory tool, improving the diagnostic accuracy of AAM." (PMID 38793100, 2024). "PRAME expression can be readily detected using the immunohistochemical method, as demonstrated in this study, and it may be particularly useful for differentiating malignant tumors, notably malignant melanomas, from benign melanocytic nevi." (PMID 38132219, 2023). "PRAME could thus be used as a target for immunotherapy in melanoma patients." (PMID 35565234, 2022). "However, several studies have shown that ZNF717, HIP1, and several genes from the PRAME (Preferentially Expressed Antigen In Melanoma) family might be involved in cognitive development, learning disorders, and developmental disorders with autistic features." (PMID 35627305, 2022). "Notably, overexpression of PRAME has been observed in malignant melanoma (88% of primary lesions and 95% of metastases), lung carcinoma (46% of adenocarcinomas and 78% of squamous cell carcinomas), renal cell carcinoma, neuroblastoma, myxoid liposarcoma, and synovial sarcoma." (PMID 32704057, 2020). "What is more, chidamide could induce the expression of the leukemia-specific antigen PRAME (preferentially expressed antigen in melanoma) in both cell lines and leukemia blasts from patients, resulting in increased PRAME-specific and CTL-mediated cytotoxicity against leukemia in vitro." (PMID 34504867, 2020). "Similarly, reduced expression of PRAME enhances the sensitivity of melanoma cells to retinoic acid." (PMID 23409080, 2013).